KRT18 (keratin 18)
Diseases named in the same sentence as KRT18 in open-access papers (continued):
Sharing a sentence is not in itself a finding about the gene and the disease.
melanoma (15 papers, 2012 to 2025). A malignant, usually aggressive tumor composed of atypical, neoplastic melanocytes. "KRT expression has long been related to migration, invasion, and progression; some recent work with melanoma cell lines has supported such a role, and KRT18 mRNA detection is associated with a poor prognosis in melanoma cases." (PMID 22829910, 2012). "Furthermore, the current study not only elucidated the anti-melanoma effect of honokiol, but also provided a detailed molecular mechanism associated with its inhibitory effect on KRT18." (PMID 33330500, 2020). "It acts as an inhibitor of the oncogenic protein KRT18 in melanoma and prevents the progression of highly metastatic melanoma." (PMID 40943669, 2025). "It slowed down the invasion of melanoma cells via lowering the concentration of the oncogenic protein 18 (KRT18) and degradation through ubiquitination, which consequently limited in vitro and in vivo growth of melanoma cells." (PMID 40943669, 2025). "It has also been shown to bind to overexpressed KRT18 in melanoma cells, leading to reduced KRT18 protein levels and consequent suppression of tumor growth both in vitro and in xenograft models." (PMID 41296425, 2025). "Honokiol inhibits the oncogenic KRT18 protein in melanoma and prevents recurrence of advanced melanoma using the β-catenin/MITF axis via prompt calpain-10 and CCAAT homologous protein (CHOP/GADD153) regulated cascades." (PMID 40943669, 2025). "We also discovered that honokiol directly interacts with keratin 18 (KRT18), inhibiting melanoma growth by inducing KRT18 ubiquitination and degradation." (PMID 39048965, 2024). "Our study demonstrates that KRT18 plays an oncogenic role in melanoma and promotes melanoma growth, while honokiol can be an inhibitor for KRT18." (PMID 33330500, 2020). "In summary, our study revealed that honokiol inhibits melanoma growth both in vitro and in vivo by targeting KRT18." (PMID 33330500, 2020). "In melanoma, a significant increase in the KRT18 mRNA level and its prognostic significance has been reported." (PMID 33330500, 2020). "To investigate the role of KRT18 in melanoma, we knocked-down or overexpressed KRT18 in melanoma cells." (PMID 33330500, 2020). "Overall, our results indicate that KRT18 is highly expressed in the melanoma tissues, at both mRNA and protein levels." (PMID 33330500, 2020). "Together, these results suggest that the growth inhibitory effect of honokiol depends upon KRT18 protein level in melanoma." (PMID 33330500, 2020). "We evaluated the effects of honokiol on melanoma growth after knocking-down or overexpressing KRT18 in melanoma cells and then treating them with honokiol." (PMID 33330500, 2020). "Our results showed that honokiol treatment significantly decreased KRT18 protein level and suppressed the tumor growth in melanoma cell-derived xenograft mice models." (PMID 33330500, 2020). "Since zebrafish represents a unique experimental model organism for studying melanoma development, progression and treatment, the teleost krt18 gene could also be considered in the melanoma clinical research." (PMID 36949761, 2023). "Hence, KRT18 play an oncogenic role in melanoma and honokiol can effectively inhibit the growth of melanoma." (PMID 33330500, 2020). "Furthermore, western blotting results showed higher expression of KRT18 in some melanoma cell lines than that in the normal skin cell." (PMID 33330500, 2020). "Our results showed higher expression KRT18 protein in melanoma compared to normal skin tissues." (PMID 33330500, 2020). "Furthermore, melanoma cells with KRT18 stable knockdown or overexpression were treated with 0, 30 or 50 μM honokiol." (PMID 33330500, 2020). "Furthermore, knockdown of KRT18 significantly decreased the proliferation of melanoma cells and their colony forming ability, indicating the oncogenic role of KRT18 in melanoma progression." (PMID 33330500, 2020).
melanoma (continued). "Furthermore, IHC staining using a melanoma tissue array, showed that KRT18 is significantly overexpressed in the melanoma tissues compared to the normal skin tissues." (PMID 33330500, 2020). "Furthermore, the expression of KRT18 was found to be higher in melanoma tissues compared to the normal skin tissues." (PMID 33330500, 2020). "Hence, to verify the interaction between KRT18 and honokiol in melanoma, we performed in vitro pull-down assay by incubating SK-MEL-5 or SK-MEL-28 cell lysates with honokiol." (PMID 33330500, 2020). "In addition, KRT18 mRNA level was found to be higher in the metastasis melanoma tissues than in the primary melanoma tissues in the TCGA database." (PMID 33330500, 2020). "Interestingly, the expression of KRT18 was comparatively higher in the melanoma tissues of male patients than their female counterparts." (PMID 33330500, 2020). "Thus, honokiol decreases KRT18 protein level by inducing its degradation through ubiquitination, in melanoma cells." (PMID 33330500, 2020). "Cytokeratin 18 is usually found in the epithelial cells and is not expressed in normal melanocytes; however, some studies have associated its presence in melanoma cells with a worse prognosis." (PMID 23701745, 2013). "Honokiol could pull down KRT18, suggesting KRT18 to be a potential target of honokiol in melanoma." (PMID 33330500, 2020). "Hence, KRT18 plays an oncogenic role in melanoma and honokiol can be an inhibitor for KRT18." (PMID 33330500, 2020). "In addition, KRT18 overexpression significantly promoted melanoma cell proliferation and growth." (PMID 33330500, 2020). "However, the biological role of KRT18 is seldom reported in melanoma." (PMID 33330500, 2020). "The results showed that knocking down of KRT18 significantly inhibited both cell proliferation and anchorage-independent colony formation of SK-MEL-5 and SK-MEL-28 melanoma cells." (PMID 33330500, 2020). "However, the functional role of KRT18 in melanoma remains unclear." (PMID 33330500, 2020). "In HUVECs co-cultured with melanoma cells there was a marked decrease in expression levels of several endothelial markers (KRT7, KRT18, TJP2), as well as a severe decrease in FST expression, an EMT/EndMT antagonist." (PMID 25742314, 2015). "Previously, HK did not alter KRT18 gene expression but decreased KRT18 protein levels in melanoma cells by promoting its degradation via ubiquitination." (PMID 41296425, 2025). "Given the apparent aberrant expression of typical melanocytic differentiation markers (such as TYR, MLANA), we chose to stain potential melanoma CTCs for pan-KRT, which is generally expressed in melanomas and has prognostic significance (particularly KRT18; see Discussion)." (PMID 22829910, 2012). "In our hands, all melanoma cell lines we generally use in the lab strongly express KRT18 (data not shown), and similar reports for KRT18 expression in cell lines are also in the literature." (PMID 22829910, 2012).
diabetes (14 papers, 2014 to 2025). "In more details, the NAFLD diagnostic panel recommended five markers (diabetes, gender, BMI, triglycerides and cytokeratin-18 (CK18) fragments) and performed better than the NASH diagnostic that included three biomarkers (CK18, adiponectin and resistin) for NASH prediction." (PMID 31163711, 2019).
ovarian carcinoma (13 papers, 2010 to 2025). A malignant neoplasm originating from the surface ovarian epithelium. "Epithelial cells and fibroblasts were the two major populations derived from primary ovarian cancer tissue, which can be differentiated by keratin 18 stain." (PMID 30319732, 2018). "We identified TF encoding genes that were putatively controlled by PEs common to the keratin group (KRT8, KRT13, KRT18), and are also previously reported to be at least 5-fold over-expressed in early and late stage ovarian cancer." (PMID 20181230, 2010). "KRT7 7, KRT18 and KRT19 are differentially expressed in circulating tumor cells in ovarian cancer patients." (PMID 29721183, 2018). "Overexpression of Snail in ovarian cancer cells induced mesenchymal markers, such as tea-shirt zinc finger homeobox (TSHZ1), collagen type Vα, and fibrillin-1 (FBN-1), while suppressing E-cadherin, myosin-5C, keratin-18, keratin-8, annexin-A3, and suppressor of tumorigenicity 14 (ST14)." (PMID 26356073, 2015).
Hepatitis (12 papers, 2011 to 2025). Inflammation of the liver. "A meta-analysis of elevated serum cytokeratin-18 levels in hepatitis showed its clinical value for identifying the development of hepatitis." (PMID 27788241, 2016).
non-alcoholic fatty liver disease (12 papers, 2013 to 2025). "Cornus mas L. fruit causes a significant decrease in cytokeratin 18 levels when treated for non-alcoholic fatty liver disease." (PMID 40432961, 2025). "The cytokeratin 18 (CK18) fragment, as a cell death marker, plays an important role in nonalcoholic fatty liver disease (NAFLD)." (PMID 32337295, 2020). "Fibroblast growth factor 21 (FGF21) and cytokeratin 18 (CK18) were previously reported to be elevated in nonalcoholic fatty liver disease (NAFLD)." (PMID 28698650, 2017).
alcoholic hepatitis (10 papers, 2010 to 2024). Acute hepatitis resulting from ingestion of alcohol. "Mallory-Denk bodies, the hallmark of alcoholic hepatitis and steatohepatitis, contain cytokeratin-18 (CK-18) and cytokeratin-19 (CK-19), while the serum CK-18 and CK-19 levels were increased in AH patients in previous studies." (PMID 34068269, 2021). "The plasma levels and EVs of cytokeratin-18 fragments (M30 and M65) are reliable non-invasive markers of alcoholic hepatitis High levels of CD34+ and ASGPR1+ EVs can be used as markers of non-response to corticosteroid therapy in severe alcoholic hepatitis." (PMID 36555854, 2022).
metabolic syndrome (10 papers, 2011 to 2026). A cluster of metabolic risk factors for CARDIOVASCULAR DISEASES and TYPE 2 DIABETES MELLITUS. "Administration of AZA induced hepatorenal dysfunction, evidenced by dyslipidemia, elevations in serum liver enzymes, creatinine, urea, pro-inflammatory cytokines, and cytokeratin-18." (PMID 40432961, 2025). "It is known that resistance activities such as push-ups or squats have effects on metabolic syndrome and lead to insulin sensitivity improvement and ALT reduction, and decreases in the cytokeratin 18 (CK18) and FGF21 levels were observed after applying this type of PA." (PMID 36902639, 2023).
non-small cell lung carcinoma (10 papers, 2010 to 2025). A group of at least three distinct histological types of lung cancer, including non-small cell squamous cell carcinoma, adenocarcinoma, and large cell carcinoma. "Increased expression of EGR1 in human non-small cell lung carcinomas is associated with up-regulation of KRT18 and reduced lymph node metastasis." (PMID 30566430, 2018). "KRT18, a cytoskeletal protein, plays a role in non-small cell lung cancer, as knocking down KRT18 results in decreased migratory ability of tumor cells." (PMID 40295497, 2025).
chronic hepatitis C (9 papers, 2011 to 2024). "In particular, the progression of chronic hepatitis B virus infection is considered to associate with the phosphorylation of KRT18, whereas the cleavage of KRT18 was shown to correlate with the stress response in livers of chronic hepatitis C patients." (PMID 31216713, 2019).
liver cancer (9 papers, 2011 to 2025). An epithelial or non-epithelial malignant neoplasm that arises from the liver. "However, only one study has reported a potential association between the KRT8/KRT18 ratio and liver cancer." (PMID 39991825, 2025). "KRT18, a type I intermediate filament protein, is essential for maintaining cell cytoskeleton and has been reported to be upregulated in several malignancies, including gastric, colorectal, and liver cancers." (PMID 41200204, 2025).
liver cirrhosis (9 papers, 2011 to 2025). "The loss and mutations of KRT18 contribute to the phenotypes of several human diseases, including skin disorders, chronic renal disease, and liver cirrhosis." (PMID 35456240, 2022). "Keratin 18 (K18) and caspase‐cleaved K18 (cK18) are established markers of epithelial cell death, with a well‐documented association with liver damage and fibrosis stages in various etiologies and clinical outcomes in liver cirrhosis." (PMID 39533838, 2025).
Sepsis (9 papers, 2009 to 2022). Sepsis is defined as life-threatening organ dysfunction caused by a dysregulated host response to infection. "For severe septic patients with liver dysfunction, a cut-off value for caspase-cleaved and uncleaved cytokeratin-18 could be calculated, in order to identify patients at high risk for death due to severe sepsis." (PMID 19538738, 2009). "Hofer and colleagues examine the importance of the clinical biomarker cytokeratin-18 (CK-18) for predicting clinical outcomes in sepsis." (PMID 35907792, 2022). "The pilot laboratory study revealed that urine caspase-cleaved cytokeratin-18 epitope M30 indicative of renal tubular cell apoptosis could be a potential early biomarker of AKI among patients without severe sepsis." (PMID 26918334, 2016). "Despite the promising results in the pilot study, urine caspase-cleaved cytokeratin-18 epitope M30 level measured at ICU admission was not significantly higher among patients developing AKI compared to non-AKI patients regardless of the presence of severe sepsis or CKD." (PMID 26918334, 2016).
bladder cancer (7 papers, 2018 to 2023). "The relevant theoretical results were also verified by detecting cytokeratin 18 (CK18, bladder cancer biomarker)." (PMID 36832021, 2023). "Noninvasive biomarkers of bladder cancer have been found to monitor the prognosis of normal bladder cancer, such as cytokeratin 18 protein fragment." (PMID 32411234, 2020). "Treatment of the explanted, cultured bladder cancer tissues ex vivo with 100 nM gemcitabine significantly decreased the number of intact KRT18-positive tumor cells (P ≤ 0.01)." (PMID 30333957, 2018).
cervical carcinoma (7 papers, 2009 to 2023). A carcinoma arising from either the exocervical squamous epithelium or the endocervical glandular epithelium. "Studies have shown that reduced KRT18 expression enhances the susceptibility of cervical cancer cells to cytokine-induced cell death, inhibits cell migration, and enhances the sensitivity to paclitaxel in LC." (PMID 37671155, 2023). "The results showed that the expression of FSCN1 had a significant negative correlation (P < 0.05) with that of HLTF, HBP1, ZNF664, CTGF, DDX17, and KRT18 in cervical cancer tissues." (PMID 35178306, 2022). "The reorganization of VIFs was also examined in human cervical carcinoma HeLa cells that express both vimentin and keratin 18 (a type I cytokeratin)." (PMID 30696956, 2019). "Increased KRT18 expression has been reported to inhibit cytokine-induced death of cervical cancer cells but there are no evidences about the role of KRT18 in L-OHP-induced resistance in CC." (PMID 23865481, 2013).
co-infection (7 papers, 2018 to 2024). "HIV-infected adults without significant alcohol intake or co-infection with hepatitis B or C underwent a routine screening program employing transient elastography (TE) with controlled attenuation parameter (CAP) and the serum biomarker cytokeratin-18 (CK-18)." (PMID 29381754, 2018).
viral hepatitis (7 papers, 2013 to 2022). An acute or chronic inflammation of the liver parenchyma caused by viruses. "The study is limited by its retrospective design in which several variables such as medication groups, details on other liver conditions such as viral hepatitis, biomarkers of NAFLD severity (such as cytokeratin 18 fragment, interleukins, tissue necrosis factor) and genetic data were not collected." (PMID 35385529, 2022).
chronic hepatitis (6 papers, 2009 to 2018). An active inflammatory process affecting the liver for more than six months. "Krt18 mutant mice develop chronic hepatitis and hepatocyte fragility in association with disruption of hepatocyte keratin filaments mouse models." (PMID 27955658, 2016). "The proteins, cytokeratin 18 and annexin 5 were confirmed to contribute to the increased relative abundance in the liver proteome of dogs with chronic hepatitis (n = 7, n = 4) compared to healthy controls (n = 7, n = 4), respectively." (PMID 30500850, 2018). "Upregulation of cytokeratin 18 in chronic hepatitis may suggest increased hepatocellular apoptosis and necrosis, whereas upregulation of annexin 5A suggests increased hepatocellular apoptosis." (PMID 30500850, 2018).
esophageal cancer (6 papers, 2008 to 2022). A primary or metastatic malignant neoplasm involving the esophagus. "Our study indicated that the knockdown of keratin 18 can enhance tumor cell migration and invasion in esophageal cancer." (PMID 25973684, 2015). "Taken together, the results of our animal study indicated that OC elevates the expression of keratin 18, inhibits activation of AKT and ERK, and suppresses pulmonary metastasis of esophageal cancer cells without significant potency in mice." (PMID 25973684, 2015).
lung adenocarcinoma (6 papers, 2013 to 2024). A carcinoma that arises from the lung and is characterized by the presence of malignant glandular epithelial cells. "Immunohistochemical characterization of six tumor regions was done for ALK and markers of lung adenocarcinoma (NKX2.1), epithelial (E‐cadherin, pan‐cytokeratin, and cytokeratin 18) and mesenchymal (vimentin) phenotypes, tumor vasculature (CD31), and basement membrane organization (collagen type IV)." (PMID 36423211, 2023).
acute liver failure (5 papers, 2011 to 2023). Rapid deterioration of liver function causing encephalopathy and coagulopathy. "In acute liver failure, the cytokeratin 18-based modification of the model for the End-Stage Liver Disease (MELD) score improves prediction of spontaneous survival after acute liver injury." (PMID 21445263, 2011).
lymph node metastasis (5 papers, 2018 to 2024). "We further investigated the clinical significance of KRT18, and observed high KRT18 expression was positively associated with clinical stage, tumor invasion depth, lymph node metastasis, distant metastasis, and degree of differentiation." (PMID 31345960, 2019). "Moreover, univariate Cox regression analysis revealed that clinical stage (P=0.004), tumor invasion depth (P=0.022), lymph node metastasis (P=0.009), distant metastasis (P<0.001), family history (P=0.042), and KRT18 expression (I–IIA vs. IIB–IV, P<0.001) were prognostic factors for CRC patients." (PMID 31345960, 2019).
metastatic disease (5 papers, 2009 to 2024). "We found epithelial marker genes, Krt18, Epcam, Dsp, were downregulated in the metastatic tumors, while genes that promote EMT, Zeb2, Loxl2, and Plau were upregulated." (PMID 31881983, 2019). "Immunohistochemical examination demonstrated that the tumor cells were positive for glypican-3 (GPC3), alpha-fetoprotein (AFP), hepatocyte paraffin-1 (Hep Par 1), cytokeratin 18 (CK 18), and hepatocyte antigen, which confirmed that the seminal vesicle tumor was a metastatic tumor of HCC." (PMID 21443783, 2011). "Notably, we found that proteins involved in triple‐negative breast cancer (TNBC), such as GSTP1 and EPCAM, were enriched in ERα‐N metastatic tumours, while proteins typically upregulated in ERα‐P disease, such as ALCAM and KRT18, were enriched in ERα‐P as well as the ERα‐C metastatic tumours." (PMID 37854018, 2024).
SARS-CoV infection (5 papers, 2020 to 2025). "Initially developed to model lethal SARS-CoV infection, the K18-hACE2 mouse model expresses hACE2 under the control of the epithelial cell cytokeratin-18 (K18) promoter, allowing for high-level expression of hACE2 in epithelial cells." (PMID 41012604, 2025).